IL6 (interleukin 6)
Diseases named in the same sentence as IL6 in open-access papers (continued):
Sharing a sentence is not in itself a finding about the gene and the disease.
Anxiety (continued). "Notably, the control group also reported a decrease in IL-6 levels; however, without improvements in the degree of anxiety or functional ability." (PMID 38921006, 2024). "The IL-6 diurnal index did not correlate with HSCL anxiety and depressive symptoms." (PMID 37324818, 2023). "Furthermore, high TNF-α (P<0.001, adjusted P <0.001) and increased IL-17 (P=0.014, adjusted P=0.056), but not IL-1β (P=0.648, adjusted P=1.000) or IL-6 (P=0.131, adjusted P=0.524), were correlated with increased anxiety severity grade." (PMID 35239774, 2022). "Since in previous study we showed the ability of Oxo treatment to abolish the anxiety-like behavior induced by CRS7, the findings of the present work clearly showed that chronic Oxo treatment may counteract the CRS effects on IL-1β and IL-6 levels." (PMID 31578381, 2019). "In addition, previous clinical research confirmed that cytokines, namely TNF-α and IL-6, induce depressive mood, anxiety, impaired memory, and lack of concentration." (PMID 31251788, 2019). "Post hoc comparisons revealed that non-obese patients diagnosed with anxiety or mood disorders (A/MD subgroup) had significantly higher mRNA levels of IL-1β (P < 0.01), IL-6 (P < 0.01) and PLAUR (P < 0.001 and P < 0.05, respectively) than non-obese patients without mental disorders (non-MD)." (PMID 30504920, 2018). "While there is general agreement in the literature about the link between an enhancement of IL-6 levels and the induction of anxiety (See revision on), the decrease of IL-6 levels was not effective in blocking the anxiogenic consequences of social defeat in our study." (PMID 30557308, 2018). "In summary, a possible mechanism for early exercise‐induced neuroprotection against PSA was through regulation of inflammation to promote neurologic recovery and ameliorate anxiety‐like behavior, and proinflammatory cytokines (PAF, IL‐6, and TNF‐α) may play a critical role in the process." (PMID 29201553, 2017). "However, an excessive cytokine response in the brain is associated with prolonged sickness behavior, cognitive deficits, and increased anxiety; and the specific role of IL-6 has not been extensively studied." (PMID 21595956, 2011). "In the present study, the proinflammatory cytokines IL‐6 and TNF‐α affected both emotions and anxiety, but unlike the anti‐inflammatory cytokines IL‐10 and ADPN, they were not related to physical disease severity." (PMID 40700022, 2025). "Before treatment, significant differences were observed in IL-1, IL-6, TNF-α, LPS, Zonulin, DAO, and I-FABP between patients with FD accompanied by anxiety and those without anxiety (p < 0.05)." (PMID 40606168, 2025). "On the other hand, quercetin inhibited nicotine-triggered CPP reinstatement, alleviated METH-induced anxiety-like behavior in mice, attenuated the activation of astrocytes, and reduced the levels of IL-1beta and TNF-α, but not IL-6." (PMID 37112606, 2023). "Negative correlations with baseline IL-1ra, IL-6, and IGFBP3 with changes in the BPRS-E manic and anxiety scores." (PMID 37763150, 2023). "Similar ICC estimates were obtained for anxiety (ICC = 0.67), perceived stress (ICC = 0.72), negative affect (ICC = 0.61), sleep disturbance (ICC = 0.58), IL-6 (ICC = 0.64), sTNF-RII (ICC = 0.73), and CRP (ICC = 0.84)." (PMID 34873150, 2021). "In our correlational analyses, a negative association was observed between IL‐6 and TNF‐α levels and time spent in open arm and exploration time of central regions and indicated that proinflammatory cytokines may be involved in the pathophysiology of anxiety‐like behavior." (PMID 29201553, 2017). "A strongly negative correlation was observed between cytokines (PAF, IL‐6, and TNF‐α) and anxiety‐like behavior (time spent in open arm and exploration time of central regions)." (PMID 29201553, 2017).
Anxiety (continued). "Exploratory random forest models tentatively identified IL-6, IL-23, FIB-4, HOMA-IR, and waist circumference as the strongest contributors to variance in depressive symptoms, while no clear contributors emerged for anxiety." (PMID 41601492, 2026). "Experimental studies also show that IL-6, IL-1β, and TNF-α rise in response to acute psychosocial stressors such as the Trier Social Stress Test, and that IL-6 correlates with negative affect and stress-related anger or anxiety." (PMID 41333345, 2025). "Besides being related to the neurobiology of anxiety, in our results, we did not observe CUS-induced alterations in IL-6 levels in the PFC, nor in the hippocampus." (PMID 36035219, 2022). "We previously demonstrated elevated cortical IL-6 in response to VILI; however, it is not known whether the acute inflammatory response of VILI contributes to acute neuropsychiatric impairments, such as delirium- and anxiety-like behaviors." (PMID 36100846, 2022). "Taken together, trauma that induces PTSD-like features in nonhuman animals increase IL-6 and treatments that reduce anxiety after trauma also reduce IL-6, so it follows that IL-6 may play a role in the mechanism of PTSD, but most data supporting this role of IL-6 are indirect." (PMID 34445252, 2021). "However, only IL-6 and TNF-α cytokines were identified as relevant pro-inflammatory biomarkers that could differentiate between the groups exhibiting affective symptoms (depressive versus the anxiety/non-depressive group) and the control group." (PMID 30943938, 2019).
hepatocellular carcinoma (577 papers, 1997 to 2026). A malignant tumor that arises from hepatocytes. "The prediction model based on serum CD147, IL-6, and other risk factors for the invasion and metastasis of primary hepatocellular carcinoma demonstrates high diagnostic value." (PMID 40919145, 2025). "Genetic variations in the IL-6 promoter region, particularly the SNPs rs1800796 (-572 G/C) and rs10499563 (-6331 T/C), have been associated with immunological regulation of hepatocellular carcinoma and other inflammatory pathologies." (PMID 40881695, 2025). "In patients with hepatocellular carcinoma, levels of IL-6 are increased and are closely linked to disease occurrence and prognosis." (PMID 39908263, 2025). "M2d cells release IL-6, a cytokine that has been associated with the development of different tumor types, including hepatocellular cancer." (PMID 39796695, 2024). "The association between PGRMC1 and EGFR was linked with NF-κB activity stimulation in a murine model of hepatocellular carcinoma, resulting in increased proinflammatory interleukin-6 (IL-6) production." (PMID 38804287, 2024). "Elevated levels of interleukin-6 (IL-6) have been documented in the bloodstream across various hepatic disorders susceptible to the development of hepatocellular carcinoma (HCC)." (PMID 37762066, 2023). "Arthrospira has the potential to not only restore immune tolerance but also reduce the risk of the hepatic carcinoma development due to decreasing the IL-6 level, liver stiffness, and hepatic steatosis in CHB patients." (PMID 35889747, 2022). "IL-6 is released by macrophages associated with adipose tissue, and stimulates cell growth in hepatocellular carcinoma mouse models through STAT3, ERK, and JNK activation and alterations in AKT and mTOR." (PMID 36038791, 2022). "In a recent study, IL-6 rs2069837 was investigated in connection with susceptibility to hepatocellular carcinoma (HCC)." (PMID 35368020, 2022). "Cytokines produced by these resident as well as infiltrating macrophages such as TNFα, transforming growth factor β (TGF-β), interleukin 6 (IL-6) and 18 (IL-18) are highly associated with the development and progression of hepatocellular carcinoma (HCC)." (PMID 36276076, 2022). "In the context of hepatocellular carcinoma, for example, IL-6 promotes resistance to sorafenib and is associated with poor prognosis." (PMID 35356749, 2022). "The continuous activation of the IL6 pathway is associated with liver injury and hepatocellular carcinoma." (PMID 36558908, 2022). "In the case of IL-6 or IL-22, it prevents fibrogenesis but promotes hepatocellular carcinoma, so the risk of tumor occurrence should be considered in the treatment of patients with hepatic fibrosis." (PMID 33841164, 2021). "For example, tumor-associated macrophages (TAMs) produced IL6 to promote expansion of CSCs via STAT3 signaling in human hepatocellular carcinoma." (PMID 33576874, 2021). "Interleukin (Il) 10, Il6 or Cd274 (PD-L1) can basically be expressed by hepatoma cells, cancer-associated fibroblasts, TAMs or MDSCs, which promote tumour growth, metastasis and immune evasion." (PMID 34830835, 2021). "This study was aimed to evaluate the association between interleukin-6 (IL-6) gene polymorphisms and the risk of hepatocellular carcinoma (HCC) in a meta-analysis." (PMID 33327352, 2020). "We aimed to evaluate the frequency of Interleukin-6 mutations (rs2069837 and rs17147230) associated with genetic risk of hepatocellular carcinoma in Khyber Pakthunkhwa population." (PMID 32266003, 2020). "Hepatocellular carcinoma-associated fibroblasts (CAFs or TAFs), has been shown to induce MDSCs generation through the IL-6/STAT3 axis and stromal cell-derived factor (SDF)-1α secretion." (PMID 31500650, 2019). "YAP can induce the expression of IL-6 in hepatocellular carcinoma cells and then recruit tumor-associated macrophages." (PMID 31299894, 2019).
hepatocellular carcinoma (continued). "It has also been reported that AR activation is associated with carcinogenesis in human hepatocellular carcinoma and pancreatic cancer with enhanced IL-6 signaling." (PMID 31836734, 2019). "The majority of DEGs, involved in the pathway “Hepatitis C and Hepatocellular carcinoma”, encode pro-inflammatory proteins (IL-6, IL-8, PTGS2), and, therefore, this term should be also considered as inflammation related." (PMID 31523389, 2019). "It has been reported that circulating IL-6 is a risk indicator and is strongly correlated with adverse prognosis in hepatocellular carcinoma (HCC)." (PMID 28430601, 2017). "TIM-3 is upregulated by TGF-β on tumor-associated macrophages (TAMs) of the M2 phenotype and ligation of TIM-3 leads to increased NF-κB and IL-6 production and is associated with reduced survival in human hepatocellular carcinoma." (PMID 28515726, 2017). "Higher circulation levels of IL-6 were significantly associated with a higher risk of developing hepatocellular carcinoma." (PMID 26808672, 2016). "IL-6 is a key event in tumorigenesis, with high levels associated with hepatocellular carcinoma (HCC)." (PMID 25665066, 2015). "Recently, it was observed that IL-6 is secreted from tumor-associated macrophages (TAMs) in hepatocellular carcinoma (HCC) and involved in the HCC tumorigenesis and also the CSC expansion." (PMID 26528857, 2015). "IL-6 is the main inducer of CRP production in vitro in cultured human hepatoma cells, but data about the associations of IL-6 and CRP in vivo is scarce." (PMID 20500875, 2010). "In addition, hepatic carcinoma-associated tumor-associated fibroblasts (TAFs) promote MDSC development via the IL-6/STAT3 signaling pathway." (PMID 40918452, 2025). "Furthermore, the study indicates that the combined elevation of TNF-α and IL-6 levels increases the risk of hepatocellular carcinoma (HCC)." (PMID 40806358, 2025). "Notably, CERS5 and CERS6 emerge as actionable enectors of IL-6 associated hepatic dysfunction: higher CERS5/6 expression correlates with reduced survival in hepatocellular carcinoma." (PMID 41256541, 2025). "Mainly, cyanidin‐3‐O‐glucoside suppresses inflammation and the production of pro‐inflammatory cytokines (COX‐2, TNF‐α, and IL‐6) in colorectal and hepatocellular carcinoma and causes cell cycle inhibition and mitochondrial dysfunction in ovarian and cervical malignancies." (PMID 40321606, 2025). "We found an increase in IL‐6 mRNA in both skeletal muscle and heart of cachectic rats, but statistical significance was not achieved likely due to experimental variability associated with the Yoshida hepatoma model." (PMID 39294861, 2024). "It has also been suggested that male-specific susceptibility to hepatocellular carcinoma is due to female protection via estrogen-mediated inhibition of IL-6 expression, as well as direct inhibition of STAT3 via estrogen-mediated expression of the tyrosine phosphatase PTPRO." (PMID 39689092, 2024). "In hepatocellular carcinoma, renal cell carcinoma, colorectal cancer, and glioblastoma increased levels of circulating IL-6 are associated with poor response to sunitinib and bevacizumab, a tyrosine kinase inhibitor targeting the VEGF/VEGFR pathway and an anti-VEGF antibody, respectively." (PMID 35626056, 2022). "Enhanced secretion of IL-6 by YAP1-activated hepatocellular carcinoma cells might induce tumor-associated macrophage maturation, and disruption of YAP1 function could suppress macrophage chemotaxis and migration." (PMID 33057010, 2020). "In conclusion, Interleukin-6 mutation is associated with hepatocellular carcinoma susceptibility." (PMID 32266003, 2020).
hepatocellular carcinoma (continued). "However, SORBS3 recently emerged as a tumor suppressor gene cooperating to inhibit interleukin-6 signaling in hepatocellular carcinoma and is associated with HCC progression." (PMID 31443224, 2019). "Human bone marrow-derived MSCs and umbilical cord MSCs caused increases in hepatoma cell migration and invasion in vitro and in 3D-culture, respectively, and this increased invasion may have been due to IL-6 secretion by MSCs." (PMID 30593276, 2018). "The importance of IL-6 signaling in promoting tumorigenesis is well-documented, particularly for tumors associated with chronic inflammation such as colitis-associated colon cancer, pancreatic cancer and hepatocellular carcinoma." (PMID 24021059, 2013). "In this respect, several studies showed that IL-6 may be a risk factor for hepatocellular carcinoma development." (PMID 21394214, 2011). "• Elevated IL-6 levels are significantly associated with advanced stages of hepatocellular carcinoma (HCC), suggesting its potential as a progression biomarker." (PMID 41379186, 2025). "Increased IL-6 levels have also been implicated in the development of hepatocellular carcinoma (HCC), as observed in both clinical and preclinical studies." (PMID 40556980, 2025). "A nested case–control study including 224 cases and 644 controls indicated higher blood IL-6 was associated with rising hepatocellular carcinoma (HCC) risk." (PMID 38339264, 2024). "TAMs may also release other ILs such as IL-6, IL-17, and IL-23 that can support tumor growth and progression as shown in models of colon cancer and hepatocellular carcinoma, in which tumor progression was associated with activation of the STAT3 signaling pathway." (PMID 38033495, 2023). "Studies of other hepatic pathogens also strongly implicate IL-6 in progressive pathogenic fibrosis and carcinogenesis, including hepatocellular fibrosis and hepatocellular carcinoma (HCC) from Hepatitis B (HBV) and Hepatitis C Virus (HCV) infection." (PMID 22629477, 2012). "In patients with hepatocellular carcinoma, there is an elevation of the pro-inflammatory interleukin il-6." (PMID 41379186, 2025). "In hepatocellular carcinoma, it has been observed that CAFs can transdifferentiate TIDCs into the rDC phenotype by activating the IL-6-mediated STAT3 pathway." (PMID 40805183, 2025). "Our data thus corroborate the possibility and reliability of using IL-6 levels as a biochemical marker of hepatocellular carcinoma." (PMID 41379186, 2025). "As NASH progresses to hepatocellular carcinoma, free fatty acids exacerbate liver inflammation via the pro-inflammatory factors IL6 and IL8." (PMID 39928768, 2025). "Previous studies observed a cytokine-mediated upregulation of CD55 and CD59 expression in human hepatoma cells in tumors mediated via pro-inflammatory cytokines such as tumor necrosis factor-alpha, IL-1 beta, and IL-6." (PMID 40723265, 2025). "Subsequent human studies further supported this trend: in early-stage hepatocellular carcinoma (HCC) resections, laparoscopic surgery was associated with lower GM-CSF, IL-6, IL-8, and MCP1 levels compared to open liver surgery." (PMID 41006707, 2025). "The interplay between KCs and exosomes derived from HCC induced KCs to differentiate into TAMs, which secreted IL6 to activate JAK1 in hepatoma cells." (PMID 39744421, 2025). "In vitro and in vivo experiments have also confirmed that the downregulation of IL-6 or MCP1 (CCL2) in hypoxia inhibits HIF-1α expression in hepatocellular carcinoma." (PMID 40430040, 2025). "For instance, TAMs in hepatocellular carcinoma have been shown to produce IL-6, which activates the STAT3 pathway, promoting the growth of CSCs and tumor progression." (PMID 40083697, 2025). "The cellular aging mechanism of IL-6 was discovered to induce aging in hepatocellular carcinoma cells by inhibiting the IL-6/signal transducer and activator of transcription (STAT) pathway via atorvastatin." (PMID 41294748, 2025).